BAP1 (BRCA1 associated deubiquitinase 1)
Diseases named in the same sentence as BAP1 in open-access papers (continued):
Sharing a sentence is not in itself a finding about the gene and the disease.
kidney cancer (28 papers, 2014 to 2025). Primary or metastatic malignant neoplasm involving the kidney. "Truncation mutations in BAP1, disrupting its peptidase region, were the predominant characteristics of kidney cancer." (PMID 39034372, 2024). "Pan-Kidney Cancer analysis for 843 RCC patients has revealed that BAP1 mutations are associated with lower survival rates in the ccRCC group, but not in PRCC or ChRCC." (PMID 38893126, 2024). "The mutations of four exons of the BAP1 gene (exons 14–17) were examined in all of the kidney cancer samples studied." (PMID 37445575, 2023). "Corresponding to the elevated CD8+ T cell presence was a higher frequency of BAP1 mutations, a feature previously associated with increased immune infiltration in a kidney cancer xenograft model." (PMID 31675502, 2019). "Thus, the combination of gender and mutation of a specific gene, such as BAP1, may have implications not only for prognosis but also for understanding the role of chromatin remodeling gene mutations in kidney cancer progression." (PMID 26484545, 2015). "A significant reduction in TMEM25 expression was observed among the mutation groups of BAP1, UNC80, EYS, SETD2 and XIRP, compared with the wild group, as BAP1 and SETD2 are commonly occurring mutation types in kidney cancer and have poor prognosis." (PMID 38189809, 2024). "Among the top 10 mutated genes found in the kidney cancer dataset, PBRM1, BAP1, SETD2, and VHL have been implicated in tumor progression and poor prognoses." (PMID 39199616, 2024). "For example, combined deletion of Vhl and Pbrm1 or Bap1 resulted in multifocal, transplantable kidney cancers arising from the proximal tubules of mice." (PMID 37217526, 2023). "Above all, ccRCC (e.g., Caki-1 cells) is accounted for in kidney-cancer-related deaths and is mutated in the von Hippel–Lindau (~90%), PBRM1 (~50%), and BAP1 (~15%) genes." (PMID 37628997, 2023). "Afterwards, we analyzed the gene mutations in the high-risk and low-risk groups of the advanced kidney cancer and discovered the mutation of some genes, such as VHL, CHEK2, BAP1, PBRM1, which were closely related to RCC." (PMID 35739510, 2022). "In BAP1-deficient ccRCC, NEAT1 competitively binds to miR-10a-5p, indirectly upregulating SERPINE1 expression to promote kidney cancer cell proliferation." (PMID 35425712, 2022). "According to the TCGA report, the most frequent gene mutations in kidney cancer were VHL, PBRM1, SETD2, and BAP1." (PMID 35055428, 2022). "In kidney cancer, BAP1 is an oncogene, provide an update on the function of the gene products, and may be exploited therapeutically." (PMID 33761933, 2021). "While a single knockout of Vhl and Pbrm1 failed to develop kidney cancer in mice, both Bap1-Vhl and Bap1-Pbrm1 double-knockout mice developed ccRCC." (PMID 40688406, 2025).
basal cell carcinoma (26 papers, 2015 to 2025). A carcinoma involving the basal cells. "Our finding raises a question regarding the role of BAP1 germline mutations predisposing to squamous and basal cell carcinomas." (PMID 29212164, 2017). "A conserved variant BAP1 p.R389C was found in a white male with CRC, squamous cell carcinoma, and basal cell carcinoma at age 66 years." (PMID 29212164, 2017). "Because of the high prevalence of both basal cell carcinomas and cutaneous squamous cell carcinomas in the general population and the unfamiliarity of the generally benign BINs, the diagnosis of BAP1-TPDS might frequently be missed." (PMID 31382694, 2019).
hepatocellular carcinoma (21 papers, 2019 to 2026). A malignant tumor that arises from hepatocytes. "In our current study, hepatocellular carcinoma tumors with low BAP1 activity scores had higher expression of bile duct signatures." (PMID 39554490, 2024). "Whether somatic mutation or expression alteration of BAP1 in hepatocellular carcinoma (HCC) influence carcinogenesis or immunogenicity is still unknown." (PMID 34976173, 2022). "The family with variant c.437+1G>T (NL-18) was initially referred by a surgeon based on familial hepatocellular carcinoma, and the occurrence of UM and MMe in this family led to genetic analysis of BAP1." (PMID 31382694, 2019). "Emerging evidence (particularly for hepatocellular carcinoma) suggests that TERT could interact with BAP1 via the WNT/β-catenin signaling pathway, which is often activated in tumors with TERT overexpression." (PMID 39858033, 2025). "Firstly, our allele induction protocol did not give rise to off-target tumours, such as those reported using similar or indeed identical allelic mice induced with high-dose adenoviral-Cre vectors, which include sarcomas, lymphomas, and, in the case of Bap1 floxed mice, hepatocellular carcinomas." (PMID 37441092, 2023). "Moreover, a cooperative manner of frequent joint inactivation of ARID2, PBRM1 and BAP1 in the subtype of hepatic carcinomas may contribute to malignancy." (PMID 36178086, 2022). "However, we did notice the occurrence of primary non-cirrhotic hepatocellular carcinoma in three proven BAP1 germline variant carriers in family NL-18." (PMID 31382694, 2019). "However, the role of BAP1 in hepatocellular carcinoma (HCC) is unclear." (PMID 39984455, 2025). "Mice with hepatic expression of mutant KrasG12D alone (KA), bi-allelic loss of hepatic Bap1 (BhomoA), and heterozygous loss of Bap1 in conjunction with mutant KrasG12D expression (BhetKA) developed primary hepatocellular carcinoma (HCC), but no discernible ICC." (PMID 34830866, 2021).
intrahepatic cholangiocarcinoma (21 papers, 2016 to 2024). A carcinoma that arises from the intrahepatic bile duct epithelium in any site of the intrahepatic biliary tree. "Surprisingly, a recent case report demonstrated that a patient with metastatic intrahepatic cholangiocarcinoma carrying a BRCA1-associated protein 1 (BAP1) mutation and RAD21 amplification benefited from PARP inhibitor treatment." (PMID 35860572, 2022). "The last group was enriched for individuals with a diagnosis of perihilar cholangiocarcinoma (PHCC) and GBC (n = 38; 79.2%), whereas patients with intrahepatic cholangiocarcinoma (ICC) were more likely to harbor IDH1-2/BAP1/PBRM1 mutations (n = 14; 60.9%)." (PMID 33297469, 2020). "Our finding that BAP1 loss is rare in PDAC whilst it is common in intrahepatic cholangiocarcinoma further reinforces the concept that they are different diseases." (PMID 26982343, 2016). "Given the close anatomical relationship between intrahepatic cholangiocarcinoma and pancreatic ductal adenocarcinoma, we therefore sought to investigate the frequency of loss of BAP1 expression in pancreatic ductal adenocarcinoma." (PMID 26982343, 2016). "Indeed, the frequency of BAP1 loss was significantly higher in intrahepatic cholangiocarcinoma when compared to extrahepatic cholangiocarcinoma and pancreatic carcinoma." (PMID 35684402, 2022). "However, the loss of BAP1 was only reported in 50% of cases of intrahepatic cholangiocarcinoma, which still leaves the question of how to classify the other 50% of cases, especially when considering that a small portion of pancreatic carcinomas also shows this loss." (PMID 35684402, 2022). "BAP1 restricted the growth cycle of intrahepatic cholangiocarcinoma by regulating ERK1/2 and JNK/c-Jun axis." (PMID 38642144, 2024). "Isocitrate dehydrogenase 1/2 (IDH1/2), BAP1, ARID1A and PBRM1 have been reported as the most frequent mutant genes in intrahepatic cholangiocarcinoma (ICC), and their relationships with clinicopathological features and prognosis were researched in this study." (PMID 32293336, 2020).
Rhabdoid Meningioma (19 papers, 2017 to 2025). A WHO grade III meningioma characterized by the predominant presence of rhabdoid cells forming sheets. "Of note, loss of BAP1 expression due to gene inactivation by mutation has been included in the WHO classification as a typical feature in high-grade rhabdoid meningiomas in association with a poorer prognosis." (PMID 38785832, 2024). "Patients with BAP1 rhabdoid meningiomas should be screened for germline BAP1 mutations to determine a predisposed risk of other malignant cancers, both for the patient and family members 55,56." (PMID 37010677, 2023). "In this regard, SMO, AKT, and PIK3CA mutations are typical of anterior skull base meningiomas, whereas KLF4 mutations are specific for secretory histology, and BAP1 alterations are common in progressive rhabdoid meningiomas." (PMID 35565385, 2022). "Regardless, our case series provide further support for the need for referral for genetic testing for patients presenting with BAP1 mutated rhabdoid meningioma." (PMID 34504799, 2021). "It is noteworthy that BAP1 germline and somatic mutations have been linked to an aggressive course in high grade rhabdoid meningiomas." (PMID 31963394, 2020). "BAP1 mutations are linked with rhabdoid meningiomas therefore its antibody might be associated with poor prognosis." (PMID 38023177, 2023). "Because BAP1 TPDS is associated with other tumors, patients with a potentially high-grade rhabdoid meningioma should be assessed for a family’s history of cancer and BAP1 status of the tumor." (PMID 33801089, 2021). "Furthermore, BAP1 an immunohistochemical marker that is lost in rhabdoid meningiomas, was retained in this case, excluding rhabdoid meningioma as a diagnosis." (PMID 41155355, 2025). "As a result, in cases of rhabdoid meningiomas, the BAP-1 status has to be assessed." (PMID 40075786, 2025). "Tazemetostat, a BAP1 inhibitor, increases the level of the PCR2 complex protein EZH2, activated by BAP1, and might be a potential drug for rhabdoid meningioma caused by BAP1 loss (NCT02860286)." (PMID 35712491, 2022). "Interestingly, a subgroup of patients with loss of expression of BAP1 have associated BRCA1 germline mutations, suggesting that patients with this mutation are also at increased risk of rhabdoid meningiomas." (PMID 33330036, 2020). "Recently it could be shown that the clinical course of rhabdoid meningiomas largely depends on the loss of the tumor suppressor BAP1, irrespective of the underlying rhabdoid phenotype." (PMID 34495383, 2021). "Additional immunohistochemistry for BAP1 in two of the three rhabdoid meningiomas showed retained immunoexpression, suggesting absence of BAP1 mutations." (PMID 34495383, 2021). "A subset of rhabdoid meningiomas reveals poor outcomes by inactivating the BAP1 gene, compared to patients with BAP1-negative rhabdoid meningiomas." (PMID 33014773, 2020).
lung adenocarcinoma (15 papers, 2015 to 2025). A carcinoma that arises from the lung and is characterized by the presence of malignant glandular epithelial cells. "The BAP1 mutation has been previously seen in two cancer cell lines, derived from a Ewing sarcoma, and a lung adenocarcinoma." (PMID 27494029, 2016). "Finally, we observed that the expression of human Bap1 mRNA was higher in normal lung samples than in lung adenocarcinoma (LUAD) samples, and it was positively associated with a better survival of LUAD patients." (PMID 35052618, 2022). "qRT-PCR analysis revealed significantly reduced expression of BAP1 in both lung adenocarcinoma (LUAD) tissues and cell lines." (PMID 40918144, 2025). "Western blot analysis revealed that BAP1 protein expression was downregulated in lung adenocarcinoma cells following miR-7974 overexpression and Circ_0007552 knockdown." (PMID 40918144, 2025). "In previous studies, most of the genes with germline mutations in lung adenocarcinoma were typical oncogenes and proto-oncogenes, which included BRCA2, CHECK2, CDKN2, BAP1, EGFR." (PMID 35712480, 2022). "The correlation between miR-31 and BAP1 was examined by evaluating BAP1 expression in human lung adenocarcinoma A549 cells after overexpression or knockdown of miR-31." (PMID 26885612, 2016). "In patients with advanced NSCLC, high BAP1 expression was found to be associated with a lack of lymph node metastasis and a longer median survival time, and deletions in the BAP1 gene were present in lung adenocarcinoma and other types of human cancers." (PMID 26885612, 2016). "Lentiviral transduction of BAP1 decreased the expression of NRF2 target genes, suppressed the migration and invasion, and sensitized cisplatin-induced apoptosis in human lung adenocarcinoma (LUAD) A549 cells." (PMID 35052618, 2022).
colorectal cancer (14 papers, 2017 to 2025). A primary or metastatic malignant neoplasm that affects the colon or rectum. "Somatic mutations in BAP1 are rare in PC, similar to breast, gastric and colorectal cancers; however, cellular localisation may be important, with nuclear BAP1 being associated with tumour aggressiveness in a subset of patients." (PMID 33557087, 2021). "It acts as a tumor suppressor and inducer of ferroptosis in colorectal cancer by modulating the miR-593-3p/BAP1 axis, thus regulating ferroptosis in colorectal cancer." (PMID 38994627, 2024). "Differential analysis of normal and cancer tissues in 11 colorectal datasets comprising 1,249 samples revealed that BAP1 mRNA expression was upregulated in colorectal cancer tissues compared to normal colorectal tissues." (PMID 36754982, 2023). "Inhibition of ASS1 can reduce proliferation of breast or colorectal cancer and moderately affected BAP1-altered MPM cells expressing ASS1, consistent with the idea that ASS1 can support MPM cell survival." (PMID 36669126, 2023).
pancreatic cancer (14 papers, 2013 to 2025). "The inactivating mutations or copy number loss of the tumor suppressor gene, BAP1, have been observed in various malignancies, including pancreatic cancer." (PMID 40083694, 2025). "Our findings elucidate the mechanism by which BAP1 inhibits the NF-κB signaling and present a promising strategy for the targeted treatment of BAP1-deficient pancreatic cancer." (PMID 40083694, 2025). "Together, our current data elucidate the promotive role of BAP1 deficiency in the proliferation, migration and invasion of pancreatic cancer." (PMID 40083694, 2025). "Mechanistically, BAP1 regulates genomic stability, in a catalytic independent manner, and its loss confers sensitivity to irradiation and platinum-based chemotherapy in pancreatic cancer." (PMID 32541668, 2020). "Consistently, human and murine BAP1-deficient pancreatic cancer cell lines showed a pronounced sensitivity and activation of ATM/ATR kinases and H2A.XSer139 phosphorylation upon different means of DNA damage." (PMID 32541668, 2020). "Here we find that genomic instability due to the loss of BAP1 is frequently observed in patients with pancreatic cancer and is associated with a history of chronic pancreatitis." (PMID 32541668, 2020). "We found that heterozygous loss of BAP1—but rarely mutation—occurs in over a quarter of PDAs and 40% of acinar cell carcinomas (ACCs), a rare and distinct subtype of pancreatic cancer that infrequently harbors KRAS mutations." (PMID 32541668, 2020). "BAP1-deficient pancreatic cancer showed numerical and structural chromosomal abnormalities and sensitivity to IR and compounds that cause replication fork stalling, such as cisplatin and camptothecin." (PMID 32541668, 2020). "Our findings above indicated that BAP1 deficient pancreatic cancer might be sensitive to the targeted inhibition of IRAK1/4." (PMID 40083694, 2025). "Thus, we were interested in investigating the anti-tumoral effect of a dual IRAK1/4 inhibitor (named IRAK1/4i) in BAP1 deficient pancreatic cancer models." (PMID 40083694, 2025). "Then, targeting IRAK1/4 could be a potential therapeutic strategy to suppress enhancive tumorigenesis in BAP1 deficient pancreatic cancer." (PMID 40083694, 2025). "It's been reported frequently heterozygous loss of BAP1 in pancreatic cancer." (PMID 40083694, 2025). "In this study, we identified BAP1 regulates tumor immune microenvironment and the sensitivity to ICB treatment in a PD-L1 independent manner, and demonstrated a potential effective strategy to overcome the un-responsiveness to ICB therapy in BAP1 deficient pancreatic cancer." (PMID 39350280, 2024). "Our findings indicate that targeted inhibition of SIRT1 or HSF1 could serve as a promising strategy to sensitize BAP1-deficient pancreatic cancer subtypes to immunotherapy." (PMID 39350280, 2024). "Although heterozygous loss of BAP1 is frequent in pancreatic cancer, the molecular mechanisms underlying this aberration in pancreas homeostasis and tumorigenesis remain unknown." (PMID 32541668, 2020). "Thus, data above suggest that BAP1 loss may lead to resistance to immunotherapy in pancreatic cancer." (PMID 39350280, 2024). "Additionally, it suggests that SIRT1 inhibition combined with ICB therapy may ameliorate the unresponsiveness of BAP1-deficient pancreatic cancer to single-agent immunotherapy." (PMID 39350280, 2024). "Thus, genomic instability due to BAP1 deficiency may be associated to the development of chronic pancreatitis and pancreatic cancer." (PMID 32541668, 2020). "BAP1 restrained the malignant progression through activating the Hippo tumor suppressor pathway in pancreatic cancer." (PMID 38642144, 2024). "CRISPR/Cas9-mediated knockout of BAP1 in PANC1 murine pancreatic cancer cells and HEK 293 T cells induced chromosome abnormalities, including chromosome breaks, shattering and aneuploidy, and these effects were exacerbated by cell exposure to IR76." (PMID 37009801, 2023).